ALB (albumin)
Diseases named in the same sentence as ALB in open-access papers (continued):
Sharing a sentence is not in itself a finding about the gene and the disease.
tumor (continued). "The strongest predictors of survival are tumor stage, volume of residual tumor after surgery, age, histological subtype, amount of ascites, preoperative albumin level, performance status, and family history suggestive of breast/ovarian cancer." (PMID 29673336, 2018). "The subgroup analyses were conducted to evaluate the prognostic values of preoperative serum albumin according to ethnicity, cut-off value, tumor type, analysis type, and sample size." (PMID 29685957, 2018). "BBB integrity was also assessed by determining leakage of Evan’s blue dye bound to albumin in control and tumor-bearing mice." (PMID 30439993, 2018). "The present study is an attempt to apply this simple strategy to develop a formulation of human serum albumin (HSA) via the copper-free cyclic Alkyne-Azide click reaction that targets tumor hypoxia." (PMID 29534020, 2018). "Univariate survival analysis method was used to analyze the sex, age, primary site of tumor, chemotherapy regimen, blood lactate level, lactate dehydrogenase level, serum albumin level, total protein level, CEA, and CA199 of mCRC patients." (PMID 30627541, 2018). "Age, BMI, tumor stage, post-operative hemoglobin concentration, and pre-operative albumin, globulin, and hemoglobin levels were statistically different." (PMID 30522461, 2018). "Previous reports have demonstrated that rapidly proliferating tumour cells actively internalize albumin for use as a source of nitrogen and energy, partially accounting for the formulation of drugs in albumin or its nanoparticles for drug delivery to tumours." (PMID 29348537, 2018). "In this study, the HAP score was a little bit high (albumin, 41.1 g/dl; bilirubin 17.8 μmol/l; tumor size, 8.6 cm; and 47% of cases with AFP > 400 ng/ml)." (PMID 29879928, 2018). "There was a sharp increase in SVV immediately after devascularization of the tumor, followed by a gradual decrease in accordance with the rapid infusion of albumin solution, but SVV was stable thereafter with a continuous infusion of norepinephrine." (PMID 32025956, 2018). "In univariate analysis, prognostic factors for an HIV-positive patient with NHL were high IPI score, poor ECOG performance status (greater than 1), advanced tumor stage and a low level of albumin." (PMID 30083224, 2018). "In this prognostic scoring system, patients with low albumin (< 36 g/dl), high bilirubin (> 17 μmol/l) or α-fetoprotein (AFP) (> 400 ng/ml), and large tumor size (> 7 cm) were associated with increased risks of death when underwent TACE." (PMID 29879928, 2018). "For size switchability, the reaction of MnO2 with H+ and H2O2 in the tumor microenvironment resulted in the gradual disassembly of HSA–MnO2 into albumin complexes with sub-10-nm sizes, achieving notably enhanced intratumoral penetration." (PMID 30340364, 2018). "The photoacoustic signal of ICG reflects extravasation of ICG-bound albumin accumulation into the extravascular space, followed by vascular hyperpermeability in tumours." (PMID 29708213, 2018). "Based on difference testing, age, BMI, tumor stage, post-operative hemoglobin concentration, and pre-operative albumin, globulin, and hemoglobin levels were entered into multivariate Cox regression analysis." (PMID 30522461, 2018). "Patients in the two age groups were all comparable for gender, tumor number, comorbidity, ability to care for themselves (ECOG PS), tumor differentiation, one-year survival, blood albumin level and tumor resection." (PMID 30450158, 2018). "After intravenous administration, this compound binds covalently to plasmatic albumin through Michael addition, thereby enabling its passive accumulation in tumours where extracellular β-glucuronidase initiates the selective release of the drug." (PMID 28507714, 2017). "Secondly, albumin nanoparticles enhance active absorption of a drug by the tumor cells via albumin receptor." (PMID 29186208, 2017).
tumor (continued). "Results showed that tumor size, albumin, PT, and AFP levels were independently associated with mortality after RFA for HCC, while tumor size, HBV-DNA, AFP levels before, and AFP response were independently associated with recurrence." (PMID 28679433, 2017). "This is firstly due to the enhanced permeation and retention effect (EPR phenomenon) of albumin nanoparticles mediated by the passive uptake of albumin in the tumor cells." (PMID 29186208, 2017). "Following internalization into tumor cells, albumin undergoes proteolytic degradation in lysosomes to provide the requisite amino acids." (PMID 27974681, 2017). "Zheng-Rong Lu's team did a remarkable work comparing biodegradable macromolecular agents of different sizes with other types of contrast agents including low molecular agents and Gd-DTPA-albumin in two tumor models." (PMID 28415647, 2017). "This feature has allowed us to exploit the ABX albumin scaffold to bind tumor-targeted antibodies, thereby increasing tumor drug deposition and tumor efficacy." (PMID 28378801, 2017). "A triple combination of anti-PD-1, albumin/AlbiVax nanocomplexes, and chemotherapeutic Abraxane that enhances tumor immunity, further inhibited the tumor progression." (PMID 29203865, 2017). "The significant risk factors for recurrence were serum albumin level, PIVKA-II, AP-factor, a higher tumor number, microscopic portal vein invasion, and microscopic hepatic vein invasion." (PMID 28830473, 2017). "Collectively, our observations define a novel function for this receptor, namely as a tumor suppressor through its ability to recycle albumin." (PMID 27974681, 2017). "Multivariate analysis identified treatment allocation, Child-Pugh class, large tumor size, albumin, and extrahepatic metastasis as independent predictors of OS." (PMID 28423370, 2017). "In clinical parameters, PC patients presented increased levels of DB and tumor markers, but a decreased level of albumin, as compared with HC." (PMID 29221120, 2017). "Conversely, Gd-DTPA-albumin had a poor performance in detecting changes in the tumor core after therapy due to low enhancement and experimental error." (PMID 28415647, 2017). "Of particular interest are the effects of different degrees of albumin excretion on these tumor markers in diabetic patients." (PMID 28744310, 2017). "Multivariable Cox proportional hazard models demonstrated that primary gender, tumor stage, albumin, LDH, ECOG score and NC / NP were independent prognostic factors of OS." (PMID 28969089, 2017). "The present study showed that tumor size, albumin, prothrombin time, and α-fetoprotein levels were independently associated with mortality after RFA for HCC, while tumor size and HBV-DNA were independently associated with recurrence." (PMID 28679433, 2017). "Previous studies have suggested that the enhanced tumor uptake of NPTX is mediated by the binding of albumin to SPARC expressed on stromal cells." (PMID 29172757, 2017). "Due to accumulation in the tumor tissue, albumin represents an important source of energy and nutrition for the tumor." (PMID 28740506, 2017). "The effects of FcRn knockdown or increased expression on albumin accumulation within the tumor cell lines suggested that the levels of FcRn would affect growth as tumor xenografts." (PMID 27974681, 2017). "Tumor size (HR = 1.36, 95% CI 1.12–1.65), albumin levels (HR = 0.76, 95% CI 0.65–0.91), prothrombin time (HR = 2.18, 95% CI 1.54–3.10), and α-fetoprotein levels (HR = 1.13, 95% CI 1.00–1.26) were independently associated with mortality after RFA for HCC." (PMID 28679433, 2017). "The factors included in multivariate analysis were tumor stage, tumor size, vascular invasion, α-fetoprotein level, albumin level, nuclear expression of FAM83H, and cytoplasmic expression of FAM83H." (PMID 28607447, 2017). "The fraction of gadolinium that is bound to albumin (or other macromolecular target) in the tumor will experience delayed washout due to the EPR effect." (PMID 29254266, 2017).
tumor (continued). "In the current study we reveal that the neonatal Fc receptor, FcRn, regulates tumor cell proliferation through the ability to recycle its ligand, albumin." (PMID 27974681, 2017). "The tumor inhibition effect of Bufalin-loaded bovine serum albumin nanoparticle was stronger than that of Bufalin alone in vivo." (PMID 28968991, 2017). "On univariate analyses, albumin, tumor multiplicity, tumor encapsulation, tumor size, vascular invasion, TNM stage, and fibrosis stage (including the Metavir and FIB-4 scores) were correlated with OS and/or RFS." (PMID 27662665, 2017). "Tumor burdens and FDG radioactivity of lung metastatic-like tumors suggest that albumin/AlbiVax significantly reduced tumor progression, and combination with anti-PD-1 further potentiated the therapeutic efficacy." (PMID 29203865, 2017). "Percentages of human albumin+ cells vary between tumours, ranging from an estimated 33% to 91% with a mean of 62% whereas adjacent non-tumour regions range from 16 to 18% with a mean of 17%." (PMID 28886065, 2017). "Meanwhile, the cationic modification of albumin, which endowed positive charges on the surfaces of the CNCs, also promoted their internalization in tumor cells." (PMID 28383524, 2017). "The results from the univariable Cox regression analysis showed that albumin, bilirubin, tumour number, tumour size, VI and aetiology were prognostic in patients undergoing TACE (all P⩽0.0001)." (PMID 28125820, 2017). "A recently developed murine model suggests improved anti-tumor efficacy with lapatinib-loaded human serum albumin nanoparticles in triple-negative BC metastasis to the brain." (PMID 28881657, 2017). "Exogenous neoantigen vaccines delivered by albumin/AlbiVax nanocomplexes can potentiate neoantigen-specific immunity and potentiate tumor therapy." (PMID 29203865, 2017). "We assumed that dye and drug tumor loading can be similar based on the physical mechanism of vessel response and presence of albumin as a pharmacokinetic “driver factor”." (PMID 28287120, 2017). "The GPS is based on the estimation of concentrations of two acute proteins: C-reactive protein and albumin; these proteins reflect the magnitude of inflammatory response arising from tumor-host interactions." (PMID 29069863, 2017). "The uptake of tumor for Bufalin-loaded bovine serum albumin nanoparticle was significantly higher than that of Bufalin both at 5 min (50.169 ± 11.708 ng/g, 93.415±13.828 ng/g, P < 0.01) and 15 min (43.683 ± 11.499 ng/g, 64.219 ± 17.684 ng/g, P > 0.05)." (PMID 28968991, 2017). "The model was built on the clinical parameters of bilirubin, albumin, tumour size and Albumin-Bilirubin (AFP), the former two presumably reflecting the impact of liver function and the latter two, the impact of tumour-related factors, on survival." (PMID 28125820, 2017). "DCE-MRI with albumin-(Gd-DTPA) 45 can detect the early effects on tumor microvasculature of a potentially curative treatment in experimental soft-tissue sarcomas." (PMID 28415647, 2017). "It is also postulated that albumin is the major covariate for the kinetics of both compounds through the vascular system and in the tumor microenvironment." (PMID 28287120, 2017). "The characteristics of the synthesized ASNPs included; intact structure of coated albumin, higher cytotoxicity against cancer cells than over normal cells, and cell death based on apoptosis and reduction of gland tumor sizes in mice." (PMID 28701707, 2017). "Folate–bovine serum albumin-functionalized polymeric micelles loaded with superparamagnetic iron oxide nanoparticles have been proposed for tumor targeting and magnetic resonance imaging." (PMID 28640222, 2017). "In contrast to the moderate inhibition of tumor progression by IFA(CpG + Adpgk), albumin/AlbiVax inhibited tumor progression significantly more effectively." (PMID 29203865, 2017).
tumor (continued). "Tumor size, albumin, prothrombin time, and α-fetoprotein levels were independently associated with mortality after US-guided RFA for HCC, while tumor size and HBV-DNA were independently associated with recurrence." (PMID 28679433, 2017). "Okuda staging and BCLC are based on tumor size and serum albumin and bilirubin levels, and the CLIP score predicts HCC based on the Child-Pugh stage, AFP level and tumor morphology." (PMID 29383172, 2017). "At the time of HCC diagnosis, group differences were observed for tumor factors, serum albumin levels (P = 0.023), and the year of HCC diagnosis (P = 0.035)." (PMID 28099520, 2017). "Given the high expression of PD-L1 on B16F10 tumor cells, a combination of anti-PD-1 and albumin/AlbiVax nanocomplexes enhanced the therapeutic efficacy." (PMID 29203865, 2017). "Binding of Gd-LC7-SH to the Cys34 residue on plasma albumin prolongs retention in the tumor microenvironment and increases tumor enhancement on MRI." (PMID 29254266, 2017). "Albumin/AlbiVax nanocomplexes are readily applicable to neoantigen vaccination for personalized tumor immunotherapy." (PMID 29203865, 2017). "After adjusting for tumor grade and TNM stage, TBIL and albumin levels were still clearly associated with OS." (PMID 28476041, 2017). "Soluble blood factors studied in CTLA-4 ICI-treated patients included S100, circulating tumor DNA, vascular endothelial growth factor, erythrocyte sedimentation rate, C-reactive protein, albumin, and lactate dehydrogenase (LDH)." (PMID 29034210, 2017). "Regarding other risk factors associated with survival of HCC after resection, microvascular invasion, tumor volume, platelet count, serum albumin, and sex have been reported to date." (PMID 29312642, 2017). "In breast tumor models, DCE-MRI with albumin-Gd-DTPA revealed a decreasing tumor vascular permeability surface area product after anti-angiogenic bevacizumab/paclitaxel combination therapy." (PMID 28415647, 2017). "Compared with the CC group, the Habib group had higher levels of γ-glutamyltransferase (P=0.044) and albumin (P=0.001), larger tumor sizes (P=0.007), shorter operation times (P=0.001), less blood loss (P=0.005), and less blood transfusions (P=0.038)." (PMID 27965468, 2017). "Prothrombin, fibrinogen, vWF, and albumin-LCFA complex are expected to extravasate into tumor tissues (number 16)." (PMID 28417928, 2017). "Tumor tissue consists of multiple components such as stromal cells, interstitial fluid, albumin, and other micro-factors such as proton and metal ions." (PMID 28417928, 2017). "While none of CpG + Trp2, AlbiCpG + Trp2, or IFA(CpG + Trp2) significantly inhibited tumor progression, albumin/AlbiVax nanocomplexes significantly prohibited tumor growth." (PMID 29203865, 2017). "The exposure of the albumin-drug conjugate to the acidic tumor microenvironment releases doxorubicin, which preferentially localizes in tumor cells that are pinocytotically-active." (PMID 27732970, 2017). "In the present work, with the aim of making specific targeting of SNPs as a drug to tumor cells and development of new anticancer agents, a novel nano-composite was developed named “albumin coated SNPs” (abbreviated as ASNPs)." (PMID 28701707, 2017). "Independent predictors of OS were treatment allocation, Child-Pugh class large tumor, albumin and extrahepatic metastasis." (PMID 28423370, 2017). "SIS was significantly associated with sex (P = 0.014), albumin (P = 0.049), ALT (P = 0.007), AST (P < 0.001), tumor size (P = 0.001) and TNM stage (P = 0.001)." (PMID 29108315, 2017). "An oxaliplatin-based platinum(iv) drug which specifically binds to albumin after i.v. application led to several complete responses in tumor-bearing mice." (PMID 28507680, 2017). "In univariate analysis, elevated AFP, γ-GT, low serum albumin, large tumor size, multiple tumors, poor tumor cell differentiation, incomplete tumor encapsulation, advanced BCLC stage, and MVI were associated with both poor OS and poor RFS." (PMID 28095820, 2017).
tumor (continued). "NLDA which was established on the pretreatment values of neutrophils, lymphocytes, D-dimer, and albumin represented the four different characteristics of the tumor microenvironment." (PMID 29137238, 2017). "Albumin/AlbiVax nanocomplexes, alone or in combination with anti-PD-1 and/or Abraxane, dramatically inhibited tumor progression in multiple syngeneic tumor models." (PMID 29203865, 2017). "We next explored albumin/AlbiVax nanocomplexes for neoantigen-based personalized tumor immunotherapy." (PMID 29203865, 2017). "The Cox multivariate analysis revealed DM (HR 1.77, 95% CI 1.24–2.51, p = 0.002), serum albumin (HR 1.67, 95% CI 1.27–2.22, p< 0.001), and total tumor volume (HR 1.51, 95% CI 1.19–1.93, p = 0.001) as independent predictors of a poor outcome." (PMID 28333991, 2017). "Like serum albumin, internalization of these matrix molecules serves to produce protein-derived amino acids that can support tumor cell growth." (PMID 29085336, 2017). "The two groups have different baseline levels of several important preoperative clinical factors, including GGT and albumin levels as well as tumor size." (PMID 27965468, 2017). "The EPR effect is, however, only one of the components contributing to enhanced albumin uptake into tumor tissue." (PMID 26988975, 2016). "It is in accordance with a recent study which verifies that increased Foxp3+ tumor infiltrating lymphocytes are related to increased serum albumin and better outcomes in stage II and III CRC." (PMID 27992611, 2016). "Among candidate markers such as ALB, tumor number × tumor size, ICG, vp, vv, platelets, PT, bilirubin, degree of differentiation, and liver damage, an optimal combination of markers was obtained." (PMID 27800494, 2016). "Future studies with larger samples, basic screening for neoplastic diseases, albumin levels, and a food intake log prior to blood collection should be considered in order to confirm the data found in this research and minimize confounding factors." (PMID 26751079, 2016). "This condition is often associated with excessive production of high-molecular-weight IGF-II from the tumor and suppressed levels of serum albumin and IGF-I." (PMID 27061182, 2016). "Increased PLR and decreased serum albumin were both associated with advanced FIGO stage (p = 0.040 and p < 0.001, respectively) and poor tumor differentiation (p = 0.010 and p < 0.001, respectively)." (PMID 26885692, 2016). "Of all significant variables, lower albumin (Hazard Ratio = 5.989, p = 0.046) and tumor numbers ≤ 3 (Hazard Ratio = 0.187, p = 0.025) played independent roles to predict patient’s mortality." (PMID 27117280, 2016). "Multivariable Cox proportional hazard models also revealed that tumor stage, palliative care, albumin level and NLR were independent prognostic factors of OS." (PMID 27510632, 2016). "It is interesting that albumin decreases as CRP increases in different tumor types, which explains the prognostic value of mGPS in various cancers." (PMID 27537502, 2016). "Consistently with these data, GSTA1 mRNA levels were negatively correlated with tumor size (P = 0.007), and positively correlated with the mRNA expression of the liver-enriched genes albumin (P = 0.001) and procollagen type XVIII (P = 0.03)." (PMID 27936036, 2016). "Univariate analysis showed that ALB level, Child-Pugh score, tumor size, TNM stage, PD1 +8669 A/G and TIM3 −1516 G/T polymorphisms were associated with OS of the patients." (PMID 27034168, 2016). "Firstly, DF-HSA can overcome serum inactivation because HBD2 is brought into the tumor cells in the albumin-integrated defensin format by macropinocytosis, evading the interference of serum." (PMID 27517152, 2016). "Activated SIR interrelates increased c-reactive protein, circulating neutrophils, NLR, mGPS, IL-6, platelets, tumor necrosis and decreased albumin, lymphocytes, hemoglobin, peritumoral infiltrate, and of course poorer survival." (PMID 27992611, 2016).